SLC7A11 (solute carrier family 7 member 11)
Diseases named in the same sentence as SLC7A11 in open-access papers (continued):
Sharing a sentence is not in itself a finding about the gene and the disease.
cancer (continued). "It occurs when cancer cells overexpress solute carrier family seven member 11 (SLC7A11), also known as xCT, leading to abnormal accumulation of disulphides (such as cysteine) in the cell due to insufficient NADPH supply under glucose starvation conditions, ultimately resulting in cell death." (PMID 37927242, 2023). "Specifically, moderate overexpression of SLC7A11 in cancer cells appears to be beneficial, in that the antioxidant effect of GSH appears to be stronger than the NADPH-depleting effect of cystine reduction; consequently, moderate SLC7A11 overexpression suppresses H2O2-induced cell death." (PMID 37339981, 2023). "However, high cystine uptake also represents a vulnerability in SLC7A11-overexpressing cancer cells." (PMID 37339981, 2023). "Previous reports showed that DMF induces ferroptosis in cancer cells, which may explain the phenomenon, as SLC7A11 is down-regulated along with the accumulation of lipid peroxidation and ferroptosis process." (PMID 36615301, 2022). "In addition, expression of the cystine/glutamate transporter SLC7A11 is upregulated in different cancers including prostate." (PMID 36280842, 2022). "This suggests that higher ROS levels in mutant-RAS driven cancers enhance dependency on GSH production for survival and that SLC7A11 associated ferroptosis suppression may support mutant-KRAS driven cancer growth." (PMID 35280777, 2022). "SLC7A11 expression is closely related to treatment resistance through multiple pathways such as the antioxidant system, nutritional limitation, autophagy, and multidrug resistance in cancer cells." (PMID 36552652, 2022). "In conclusion, there seems to be a broad and complicated link between SLC7A11 and cancer." (PMID 35804831, 2022). "SLC7A11 is a major regulator of metabolic reprogramming in normal and cancer cells." (PMID 35280777, 2022). "More interestingly, PDT activates T lymphocytes to release IFN-γ which has been proved to downregulates both system xc- subunits (SLC3A2 and SLC7A11) at the transcriptional level, thereby causing depletion of the intracellular GSH pool and triggering ferroptosis in cancer cells." (PMID 35645842, 2022). "Mechanistically, the anti-cancer effect of metformin was achieved by inhibiting the UFMylation of SLC7A11, a cysteine transporter critical for ferroptosis, implying that targeting the UFM1/SLC7A11 pathway could be a promising cancer treatment strategy." (PMID 35884562, 2022). "After chemotherapy or radiotherapy, some cancer cells may upregulate SLC7A11 expression to resist oxidative stress, inhibit ferroptosis, and develop therapeutic resistance." (PMID 35804831, 2022). "SLC7A11 is overexpressed in many cancers, especially in PAAD." (PMID 35795552, 2022). "However, SLC7A11 knockdown or pharmacological inhibition by sulfasalazine in SLC7A11high cancer cells reduces cellular ROS levels and cell death induced by glucose deprivation." (PMID 36552652, 2022). "Based on this, SLC7A11 is considered a very good anti-cancer drug target." (PMID 34996454, 2022). "This suggests that SLC7A11-high cancers, like TNBCs, are more dependent on glutamine." (PMID 35280777, 2022). "Over the years, numerous studies on SLC7A11 have given us a deeper understanding of its basic functions, regulation, and pathophysiological effects, but whether SLC7A11 is a friend or foe of cancer remains a controversial issue." (PMID 35804831, 2022). "And histone H2A ubiquitination induced by PRC1 could repress SLC7A11 expression and then regulate ferroptosis of cancer cells." (PMID 35197055, 2022). "Class I FINs are a promising anti-cancer drug for cells with high SLC7A11 expression." (PMID 34996454, 2022).
cancer (continued). "SLC7A11 negatively regulates ferroptosis progression and is overexpressed in various human cancers." (PMID 35685623, 2022). "Class I FINs aim at inhibiting SLC7A11 activity to trigger ferroptosis in cancer cells." (PMID 35368652, 2022). "Likewise, specific transcription factor 3 (ATF3) binding to the SLC7A11 core promoter region increases cancer cell sensitivity to ferroptosis." (PMID 35884471, 2022). "However, emerging evidence also suggests that on some occasions, the inhibition of SLC7A11 is beneficial to the survival of cancer cells, and confers the development of drug resistance." (PMID 35804831, 2022). "Among them, numerous studies have uncovered the role of SLC7A11 in cancer development." (PMID 35992269, 2022). "In the pan-cancer analysis, high expression of SLC7A11 showed poor overall survival in seven cancers, while the correlation between immune checkpoints (ICs) and SLC7A11 varied by cancer type, indicating the potential therapeutic effects of SLC7A11 in cancers other than LIHC." (PMID 36267158, 2022). "SLC7A11 is becoming a potential new cancer treatment target." (PMID 35309947, 2022). "In CRC, there are some studies discussing the role of FRGs, for example, activation of ATF3 may promote ferroptosis by inhibiting the Xc− system; CDKN2A sensitizes cancer cells to ferroptosis by downregulating SLC7A11." (PMID 36414988, 2022). "Therefore, the dispensability of SLC7A11 in normal systems and its high expression in various cancers makes it an attractive therapeutic target for cancer treatment." (PMID 35280777, 2022). "SLC7A11 is a ferroptosis suppressor gene that is overexpressed in many human cancers." (PMID 35574340, 2022). "A better understanding of cysteine and SLC7A11 functions regulating and interacting with redox-active proteins and their substrates could be a promising strategy for cancer treatment." (PMID 36552652, 2022). "Moreover, CD44, a cancer stem cell marker, enhances this event by increasing the interaction of SLC7A11 with OTUB1." (PMID 36289191, 2022). "Another study demonstrated that the circular RNA circ0097009 is significantly upregulated in HCC cell lines and tissues and acts as a competing endogenous RNA to regulate the expression of SLC7A11, a key regulator of cancer cell ferroptosis, by sponging miR-1261 in HCC." (PMID 35406596, 2022). "In fact, glutamate secretion by SLC7A11 may also promote the intrinsic invasiveness of cancer cells." (PMID 35804831, 2022). "Therefore, targeting SLC7A11-mediated cystine uptake to destroy antioxidative system in cancer cells with impaired glutathione synthesis or compromised transsulfuration pathway should be a feasible strategy to induce cystine auxotrophy." (PMID 35178349, 2022). "Studies have shown that SLC7A11 can promote cysteine absorption and glutathione biosynthesis, prevent oxidative stress, thus, significantly increase glutamine metabolism, and promote the growth of cancer cells." (PMID 35174151, 2022). "SLC7A11 is expressed in different tissues and plays diverse functional roles in the pathophysiology of various diseases, including cancer, by regulating the processes of redox homeostasis, metabolic flexibility/nutrient dependency, immune system function, and ferroptosis." (PMID 35280777, 2022). "SLC7A11 regulated cancer cell ferroptosis through glucose- and glutamine-dependency." (PMID 35271462, 2022). "The role of SLC7A11 in cancer has been widely studied in recent years." (PMID 35992269, 2022). "The mRNA expression level of SLC7A11 was analyzed in various cancer types." (PMID 35517862, 2022).
cancer (continued). "The potential for the therapeutic modulation of SLC7A11 activity in cancer is also discussed." (PMID 35804831, 2022). "Recently, it has been reported that anti-PD-L1 (programmed cell death-Ligand 1) immune checkpoint blockade can induce cancer cell ferroptosis responses by down-regulating SLC7A11 expression in cancer cells as a result of IFN-γ (Interferon γ) secreted by CD8+ T cells." (PMID 35309918, 2022). "Furthermore, Slc7a11-positive M2-like macrophages would be a promising therapeutic target especially for cancers that develop in chronically injured organs." (PMID 36470862, 2022). "Therefore, the SLC7A11 expression of cancer cells can be an important target for predicting resistance to anticancer drugs and overcoming treatment resistance." (PMID 36552652, 2022). "In conclusion, the biological function and regulation of SLC7A11 will attract significant attention in cancer research, and targeting the SLC7A11 pathway may provide a novel and effective therapeutic approach for anticancer therapy." (PMID 35884471, 2022). "Therefore, overexpression of SLC7A11 expression for activation of cystine uptake is observed in various types of human cancers." (PMID 36552652, 2022). "In conclusion, the SLC7A11 gene is involved in different stages of cancer development." (PMID 35804831, 2022). "This suggests the correlation between SLC7A11 and cancer development." (PMID 35399708, 2022). "Similarly, NRF2 activation in cancer cells results in increased sensitivity towards glutamine starvation and glutaminase inhibition, potentially due to increased SLC7A11-mediated glutamate export." (PMID 35280777, 2022). "Hence, SLC7A11 is expected to be a valuable prognostic signature informing future research into targeting SLC7A11 in cancer immunotherapy except in the LIHC scenario." (PMID 36267158, 2022). "Recent studies suggest high SLC7A11 expression promotes glucose dependency, which could serve as a biomarker for using GLUTi in cancer treatment." (PMID 35178349, 2022). "However, there is evidence that drugs, radiation, and other stimuli can induce cancer cells to adapt to these stress conditions by increasing the expression of SLC7A11, which is often unrelated to ferroptosis." (PMID 35645831, 2022). "While high SLC7A11 expression may be detrimental for patient outcomes in cancer, it also plays a role in healing in many tissues." (PMID 35280777, 2022). "However, BRCA1-associated protein 1 (BAP1) blocks ubiquitination of histone 2A leading to inhibition of SLC7A11 gene transcription, subsequently, increases lipid peroxidation and promotes cancer cell ferroptosis." (PMID 36289191, 2022). "Now, an intriguing question is how SLC7A11 is regulated in cancer." (PMID 35415880, 2022). "Moreover, it has been shown that glucose starvation-induced cell death in SLC7A11-high cancer cells can be prevented by restoring NADPH levels." (PMID 35280777, 2022). "Cancer cells increase SLC7A11 levels to enhance cystine import and maintain ROS homeostasis." (PMID 35280777, 2022). "In terms of the relationship between autophagy and lipid peroxidation, progesterone receptor membrane component 1 (PGRMC1) suppresses SLC7A11 via autophagic degradation of lipids, known as lipophagy, and induces ferroptosis in paclitaxel‐tolerant persister cancer cells." (PMID 35342359, 2022). "Indeed, our study has found that 25 μM of enzalutamide that imitates the real dose of enzalutamide in patients induced higher expression of cancer-related genes such as GR and SLC7A11, in comparison with 10 μM of enzalutamide." (PMID 35864113, 2022).
cancer (continued). "As both glutamine and glucose are important for the TCA cycle, it has been speculated that enhanced SLC7A11 export of glutamate in cancer cells makes them more dependent on glucose to replenish the TCA cycle." (PMID 35280777, 2022). "From this, we conclude that ferroptosis inducers targeting SLC7A11 might be new therapeutic targets for cancer patient with wild‐type BRCA by potentiating the efficacy of PARP inhibitors." (PMID 36485069, 2022). "Collectively, these studies suggest that enhanced glutamate export and NADPH investment in cancer cells upregulate SLC7A11 levels and enhance dependency on glucose and/or glutamine, though this may be cell line and context dependent." (PMID 35280777, 2022). "Similar biological properties of SLC7A11 across cancers have also been detected." (PMID 36267158, 2022). "Interestingly, overexpression of SLC7A11 enhances the antioxidant ability of some resistant cancer cells to overcome drug-induced oxidative stress and ferroptosis." (PMID 35804831, 2022). "SLC7A11 is frequently overexpressed in cancers that confer the ferroptosis resistance phenotype." (PMID 35992146, 2022). "Thus, a more thorough knowledge of the control of SLC7A11 is key to understanding cancer biology and potentiates new therapeutic targets." (PMID 35884471, 2022). "Together, these studies revealed that SLC7A11 promotes glucose dependency in cancer cells." (PMID 33000412, 2021). "It was further shown that the suppressed SLC7A11 expression results in decreased cystine uptake and GSH biosynthesis in ARID1A-deficient cancer cells, which induces a vulnerability rendering ARID1A-deficient cancers susceptible for pharmacological inhibition of GSH biosynthesis." (PMID 33000412, 2021). "Oncomine pan‐cancer analysis showed that SLC7A11 overexpression was observed in multiple cancers." (PMID 34761566, 2021). "Further, three independent databases determined that SLC7A11 expression was closely related to autophagy, and SLC7A11 was predicted to act as ceRNA for 42 autophagy genes in 32 cancer types, which account for 38.5% (42/109) of the genes in the autophagy pathway (map04140)." (PMID 34790572, 2021). "Overall, excessive expression of intra-tumoral SLC7A11 may be an unfavorable factor for patients’ prognosis in several cancers." (PMID 34938318, 2021). "Since OTUB1 is frequently overexpressed in human cancers, high SLC7A11 levels in some cancers might result from post-translational regulation by OTUB1." (PMID 33000412, 2021). "In addition, SLC7A11 overexpression was an adverse factor for the DSS of patients with eight cancers (ACC, BLCA, KICH, KIRC, KIRP, LGG, PRAD, and SKCM) (HR > 1, p < 0.05); however, it was a favorable factor for better DSS in READ (HR < 1, p < 0.05)." (PMID 34938318, 2021). "Indeed, OTUB1 is frequently overexpressed in multiple types of cancer, and OTUB1 deficiency abolishes xenograft growth in mice, which can be rescued by SLC7A11 overexpression." (PMID 34485285, 2021). "SLC7A11 plays a critical function in modulation of ferroptosis and cancer development." (PMID 34177591, 2021). "In addition to DPP4, SLC7A11 overexpression can promote glucose dependence in cancer cells to increase ROS levels and cell death." (PMID 33574983, 2021). "Cancer genomic analysis revealed that SLC7A11 is a key target gene of BAP1." (PMID 34249928, 2021). "The results indicated that SLC7A11 could potentially regulate 4595 genes acting as a ceRNA in 32 types of cancers." (PMID 34790572, 2021).
cancer (continued). "Furthermore, TPL suppressed NRF2/SLC7A11 axis and synergized with erastin to kill both GSDME-expressing and GSDME-deficient cancer cells." (PMID 34108030, 2021). "The results noted that 92.6% cancers were featured with upregulated SLC7A11 expression, which further supported our hypothesis." (PMID 34938318, 2021). "Combination of radiotherapy and immunotherapy could enhance the lipid oxidation and ferroptosis of cancer cells by synergistically targeting and suppressing SLC7A11." (PMID 34722530, 2021). "Consequently, these two “costs” associated with SLC7A11-mediated cystine uptake, namely glutamate export and NADPH consumption for cystine reduction, drive SLC7A11high cancer cells to be highly dependent on glutamine and glucose." (PMID 33000412, 2021). "SLC7A11 predominately confers ferroptosis-resistance and is highly expressed in many cancers." (PMID 34485285, 2021). "As another approach, rather than directly inhibiting SLC7A11, various studies have tested targeting metabolic vulnerabilities associated with SLC7A11high cancers." (PMID 33000412, 2021). "The results showed that SLC7A11 is overexpressed in 80% (16/20) cancers, which indicated that many cancers may shrink ferroptosis by upregulating SLC7A11 expression." (PMID 34938318, 2021). "Likewise, activating transcription factor 3 (ATF3) represses SLC7A11 expression by binding to the SLC7A11 promoter, boosting the sensitivity of cancer cells to ferroptosis." (PMID 33891303, 2021). "Moreover, overexpression of SLC7A11, which had a high expression in several cancers, including ACC, inhibited the ferroptosis induced by ROS." (PMID 34335745, 2021). "Overexpression of SLC7A11 suppresses ferroptosis —a form of regulated cell death induced by excessive lipid peroxidation—correlating with better radiotherapy response and longer survival in cancer patients." (PMID 34446045, 2021). "Hence, we elaborated the pan-cancer level bioinformatic study and systematically elucidated the role of intra-tumoral expression of SLC7A11 in the survival of cancer patients and potential immunotherapeutic response." (PMID 34938318, 2021). "Hence, it is imperative to explore the expression and clinical relevance of SLC7A11 in cancer samples." (PMID 34938318, 2021). "SLC7A11 is the gate keeper for antiporter of cystine-glutamate, also involved in cancer development, Newest study have indicated that SLC7A11 mediated the radiotherapy and immunotherapy of cancers via ferroptosis, which implied the role of SLC7A11 in regulating ferroptosis of cancers." (PMID 34122108, 2021). "In ARID1A-deficient cancer cells, GSH level decreases due to the impairment of solute carrier family 7 member 11 (SLC7A11), the gene encoding cystine transporter that is required for incorporation of cystine and supplies cells with cysteine, a key source of GSH." (PMID 34671561, 2021). "Interestingly, there were 6 cancer tissues out of 14 that expressed significant levels of both SLC7A11 and SLC3A2, which we designated xCT positive tissue, while none of the normal breast tissues was xCT positive." (PMID 33672555, 2021). "Below, we further discuss recent preclinical studies aimed to target SLC7A11 in cancer." (PMID 33000412, 2021). "Furthermore, it was found that elevated SLC7A11 expression in cancer cells drives selenocysteine biosynthesis by promoting selenite reduction and uptake as an early step in selenocysteine biosynthesis." (PMID 33672555, 2021). "Moreover, the correlation of NRF2 and SLC7A11 has been revealed from the result in almost 950 cancer cell lines." (PMID 33922165, 2021). "Moreover, SLC7A11 expression is essential for the anti-cancer toxicity of temozolomide (TMZ), a DNA alkylating agent used to treat malignant gliomas." (PMID 33401748, 2021).